PLAG1 (PLAG1 zinc finger)
Diseases named in the same sentence as PLAG1 in open-access papers (continued):
Sharing a sentence is not in itself a finding about the gene and the disease.
prostate carcinoma (3 papers, 2020 to 2025). A carcinoma that arises from epithelial cells of the prostate gland. "miR - 135b, significantly downregulated in prostate cancer, promotes bone metastasis by enhancing the migration capacity of prostate cancer cells, with PLAG1, JAKMIP2, PDGFA, and VTI1B identified as potential mediators." (PMID 40837012, 2025). "Module 2 includes TGFBR3, FOXO1, RSPO3, PLAG1, and CYLD, which have been shown to play a role in mediating or inhibiting prostate cancer progression." (PMID 39347576, 2024).
thyroid cancer (3 papers, 2014 to 2021). "In thyroid cancer, hsa_circ_0074817 targets miR-27a-3p, targeting MET, ABCA1, MMP13, and PLAG1, promoting cell proliferation, invasion, and metastasis in thyroid carcinoma." (PMID 34055888, 2021). "Moreover, it has been shown that in thyroid carcinomas the increased expression of HMGA2 and PLAG1 is detectable on the mRNA as well as on the protein level." (PMID 24516594, 2014).
chronic lymphocytic leukaemia (2 papers, 2013 to 2016). "The deregulation of miR-181a, miR-181b, miR-107 and miR-424 was found to lead to the subsequent overexpression of the oncogenic transcription factor pleomorphic adenoma gene 1 (PLAG1) in a number of chronic lymphocytic leukaemia (CLL) cases." (PMID 23478435, 2013). "Downregulation of miR-424 in treatment-naive chronic lymphocytic leukemia (CLL) patients due to epigenetic transcriptional silencing resulted in overexpression of the oncogenic transcription factor pleomorphic adenoma gene 1 (PLAG1)." (PMID 27013583, 2016).
colorectal cancer (2 papers, 2025). A primary or metastatic malignant neoplasm that affects the colon or rectum. "The hsa‐miR‐181a‐5p inhibits Wnt/β‐catenin and Pleomorphic Adenoma Gene 1 (PLAG1) pathways, enhancing the sensitivity of colorectal cancer cells to 5‐FU." (PMID 40444136, 2025). "In colorectal cancer, PLAG1 is a gene directly targeted by miR-181a/135a/302c, and then affects the IGF2 signaling pathway, regulates the proliferation and drug resistance of colorectal cancer cells, and affects their sensitivity to 5-FU." (PMID 40276502, 2025).
dwarfism (2 papers, 2016 to 2021). "In a mouse model, Plag1‐knockout mice show dwarfism and reduced fertility: Plag1−/− males impregnate wild‐type females at a lower rate and Plag1−/− females show reduced litter size." (PMID 26260584, 2016). "In contrast, PLAG1 appears the most promising causative gene for the QTL, because Plag1 knockout mice show dwarfism in the absence of other symptoms, showing consistency with the result that the bovine variant enhancing the gene expression increased withers height." (PMID 26260584, 2016). "This was consistent with the result in which PLAG1 knockout mice showed dwarfism without other symptoms, while cattle with PLAG1 gene overexpression increased in withers height." (PMID 34359192, 2021).
Insulin resistance (2 papers, 2021 to 2024). Increased resistance towards insulin, that is, diminished effectiveness of insulin in reducing blood glucose levels. "In humans, PLAG1 methylation is related to leptin concentrations in cord blood and PLAG1 expression is correlated with increased body fat mass, insulin resistance, and fatty acid concentrations." (PMID 38671859, 2024). "Nevertheless, in our study, the PLAG1 expression was not linked to the presence of insulin resistance nor the values of blood pressure." (PMID 34063412, 2021).
liver cancer (2 papers, 2014 to 2024). An epithelial or non-epithelial malignant neoplasm that arises from the liver. "Utilizing the TCGA database, we found a correlation between high PLAG1 expression and reduced survival rates among liver cancer patients." (PMID 38745179, 2024). "Our study indicates PLAG1 as a potential therapeutic target, given its increased expression levels in liver cancer tissues compared to normal ones." (PMID 38745179, 2024). "However, the role of PLAG1 in the regulation of sorafenib-induced ferroptosis in liver cancer remains a subject for further investigation." (PMID 38745179, 2024). "Previous investigations have provided evidence that sorafenib possesses the capability to induce the onset of ferroptosis in the treatment of liver cancer, thus providing the possibility of confirming the inverse regulatory relationship between PLAG1 and ferroptosis." (PMID 38745179, 2024). "Our GSEA enrichment analysis on the TCGA database indicates a strong connection between PLAG1 co-expression genes and redox reactions, suggesting GPX4 could be an influential mediator of PLAG1 in liver cancer." (PMID 38745179, 2024).
male infertility (2 papers, 2017 to 2023). The inability of the male to effect fertilization of an ovum after a specified period of unprotected intercourse. "Hypermethylation of PLAG1 has been associated with male infertility, and the PLAG1 gene deficiency can cause abnormal curling of the epididymis, impair sperm movement, and reduce fertility." (PMID 37370533, 2023).
malignant thyroid tumors (2 papers, 2014 to 2021). "Herein, we observed a strong correlation between the expression of HMGA2 and PLAG1 in 14 benign and 23 malignant thyroid tumors." (PMID 24516594, 2014).
mesenchymal tumors (2 papers, 2023 to 2025). "We report two PLAG1-rearranged mesenchymal tumors arising in adults which, although largely similar histologically to the fibromyxoid tumors reported in infants, display limited adipocytic differentiation." (PMID 40879223, 2025).
ovarian carcinoma (2 papers, 2025 to 2026). A malignant neoplasm originating from the surface ovarian epithelium. "PLAG1 silencing can inhibit the sensitivity of ovarian cancer cells to cisplatin through IGF2 signaling pathway." (PMID 40276502, 2025).
thyroid tumor (2 papers, 2014 to 2022). A benign or malignant neoplasm affecting the thyroid gland. "Spearman’s correlation coefficient thus was calculated as a measure of association between the HMGA2 and PLAG1 expression for all 37 tumor samples and resulted in a high value (ρ = 0.82, p<0.0001) indicating that the expression of both genes is strongly correlated in thyroid tumors." (PMID 24516594, 2014). "The expression levels of HMGA2 and PLAG1 are highly correlated in thyroid tumors, and HMGA2 overexpression in cellular models is associated with an increase in PLAG1 expression." (PMID 35741015, 2022). "The expression of HMGA2 and PLAG1 was quantified in 37 thyroid tumors." (PMID 24516594, 2014).
transient neonatal diabetes mellitus (2 papers, 2019 to 2021). Transient neonatal diabetes mellitus (TNDM) is a genetically heterogeneous form of neonatal diabetes (NDM) characterized by hyperglycemia presenting in the neonatal period that remits during infancy but recurs in later life in most patients. "Loss of methylation at the PLAG1 DMR during fetal development is also thought to be the causal factor for transient neonatal diabetes mellitus (TNDM)." (PMID 34444981, 2021).
Wilms tumor (2 papers, 2018 to 2022). An embryonal neoplasm characterized by the presence of epithelial, mesenchymal, and blastema components. "The authors found that pleiomorphic adenoma gene 1 (PLAG1) is one of the most consistently upregulated genes in Wilms tumors with mutations in miRNA-processing genes." (PMID 35531954, 2022). "996–1007) show that microRNA processing gene mutations in Wilms tumor lead to an increase in the levels of transcription factor pleomorphic adenoma gene 1 (PLAG1) that in turn activates IGF2 expression." (PMID 30068702, 2018). "miR-16 and miR-34, which are downregulated in Wilms tumors, were identified as potential regulators of PLAG1 expression." (PMID 35531954, 2022). "In a Wilms tumor cell line, the investigators replicated these findings, in which down-regulation of miR16/34 results in up-regulation of PLAG1, which transactivates Igf2 expression." (PMID 30068702, 2018).
benign salivary gland tumors (1 paper, 2025). "PLAG1 is closely related to benign salivary gland tumors and stromal tumors, and it can be used as a diagnostic marker for pleomorphic adenoma." (PMID 40276502, 2025).
bladder cancer (1 paper, 2025). "In bladder cancer, functional enrichment analysis indicated that PLAG1 was involved in epidermal related processes and immune pathways." (PMID 40276502, 2025). "PLAG1 gene expression reduction can significantly inhibit the proliferation of bladder cancer cells." (PMID 40276502, 2025). "The enrichment analysis and biological function of PLAG1 in bladder cancer were analyzed." (PMID 40276502, 2025).
brain tumor (1 paper, 2025). "While PLAG1 and PLAGL2 have been described as proto-oncogenes, PLAGL1 seems to act in a context dependent manner either as a tumor suppressor gene or, as recently described by us and others, as a proto-oncogene in the brain tumor context." (PMID 40751809, 2025).
carcinosarcoma (1 paper, 2024). A malignant tumor composed of a mixture of carcinomatous and sarcomatous elements. "As these translocations are mutually exclusive, it was concluded that the carcinosarcoma most likely came from another PA with PLAG1 mutation or originated de novo, thereby suggesting that the presence of PA is not conclusive of carcinosarcoma ex pleomorphic adenoma." (PMID 38243328, 2024).
developmental delay (1 paper, 2025). "PLAG1, HMGA2, and IGF1R patients exhibited a lower frequency of body asymmetry and of relative macrocephaly at birth and postnatal life, while IGF2 patients displayed an increased frequency of feeding difficulties, heart defects, skeletal malformations, and developmental delay." (PMID 39412159, 2025).
diabetic retinopathy (1 paper, 2025). "A paralog of PLAGL2, the PLAG1 gene, has recently been implicated in diabetic retinopathy." (PMID 40027191, 2025).
ependymoma (1 paper, 2016). A WHO grade II, slow growing tumor of children and young adults, usually located intraventricularly. "Poor prognostic features were found in two other patients: low expression of PAX8, FHIT, CASP10, CHD2, with high expression of CHD11, FUS, and MTA1 in a patient with Ewing sarcoma, and gain of 1q and loss of 6q and overexpression of TNC, CALB1, PLAG1, ALDH1L1, and RELN in a patient with ependymoma." (PMID 28007021, 2016).
esophageal carcinoma (1 paper, 2025). A primary or metastatic malignant neoplasm involving the esophagus. "Notably, in the BRCA, esophageal carcinoma (ESCA), COAD, and KIRC, the promoter methylation levels of PLAG1 were significantly elevated in tumor tissues." (PMID 40276502, 2025).
follicular adenomas (1 paper, 2014). "The relative expression of PLAG1 ranged between 0.2 and 19.8 in follicular adenomas and was below ten in twelve of 14 cases." (PMID 24516594, 2014).
follicular thyroid carcinomas (1 paper, 2014). "Follicular carcinomas with high HMGA2 expression levels also express PLAG1 at elevated levels." (PMID 24516594, 2014). "In the subgroup of follicular carcinomas without or with only slight HMGA2 overexpression, the PLAG1 expression levels ranged between 0.3 and 0.6 in four cases while one case showed a slight overexpression (7.4)." (PMID 24516594, 2014).
head and neck squamous cell carcinoma (1 paper, 2025). A squamous cell carcinoma that arises from any of the following anatomic sites: lip and oral cavity, nasal cavity, paranasal sinuses, pharynx, larynx, and salivary glands. "In the analysis of immune checkpoint (IC) genes, PLAG1 exhibits a positive correlation with key IC genes such as HAVCR2 and CD274 in cancer types like LGG and PRAD, while showing a negative correlation in head and neck squamous cell carcinoma (HNSC) and STAD." (PMID 40276502, 2025).
Hearing impairment (1 paper, 2025). A decreased magnitude of the sensory perception of sound. "Moreover, knockout of PLAG1 in mouse models leads to growth retardation, reduced fertility, and hearing impairment." (PMID 40276502, 2025).
Hyperglycemia (1 paper, 2017). An increased concentration of glucose in the blood. "This LOH fragment included PLAG1 and HYMAI genes, which were associated with imprinting disorder intrauterine growth retardation and neonatal hyperglycemia." (PMID 28472932, 2017).
liver tumor (1 paper, 2012). "To define the IGF signaling status in our pediatric liver tumor collection, we initially investigated the endogenous expression of the ligand IGF2 and its positive regulator PLAG1." (PMID 22401581, 2012).
lung squamous cell carcinoma (1 paper, 2025). "In contrast, in KIRC and lung squamous cell carcinoma, PLAG1 was negatively correlated, suggesting that PLAG1 may exhibit immune regulatory heterogeneity across different cancer contexts." (PMID 40276502, 2025).
macroglossia (1 paper, 2022). The presence of an excessively large tongue, which may be congenital or may develop as a result of a tumor or edema due to obstruction of lymphatic vessels, or it may occur in association with hyperpituitarism or acromegaly. "Further, chromosome 6q24 has gene imprinting regions, including PLAG1 and HYMAI genes, and abnormalities in these may lead to fetal intrauterine growth retardation, temporary neonatal diabetes, macroglossia, or umbilical hernia." (PMID 35397568, 2022).
metastatic carcinoma (1 paper, 2025). A carcinoma which has spread from the original site of growth to another anatomic site. "Fluorescence in situ hybridization (FISH) demonstrated PLAG1 gene rearrangements in both the benign nasopharyngeal lesion and the metastatic carcinoma, establishing the diagnosis of CXPA arising from a nasopharyngeal PA." (PMID 41458668, 2025). "This discrepancy prompted molecular analysis, where PLAG1 rearrangement proved essential in confirming the link between the primary PA and metastatic carcinoma." (PMID 41458668, 2025). "Fluorescence in situ hybridization (FISH) demonstrated PLAG1 gene rearrangements in both the benign nasopharyngeal PA and the metastatic carcinoma in the lymph node, confirming a diagnosis of CXPA." (PMID 41458668, 2025).
microcephaly (1 paper, 2025). A congenital or acquired developmental disorder in which the circumference of the head is smaller than normal for the person's age and sex. "This has previously been reported for HMGA2 and PLAG1, only one IGF2 case had relative microcephaly." (PMID 41430624, 2025).
myelofibrosis (1 paper, 2019). A partial or complete replacement of the bone marrow stroma by fibrous tissue. "Of note, Lin28b, but not Plag1, was also demonstrated to be up-regulated following loss of Ezh2 during the accelerated development of Jak2V617F-mediated myelofibrosis." (PMID 30890554, 2019).
papillary carcinoma (1 paper, 2014). A malignant epithelial neoplasm characterized by a papillary growth pattern. "In the follicular variants of papillary carcinomas, it ranged between 10.9 and 27.2, and in the classic variants of papillary carcinomas, the PLAG1 expression ranged between 21.3 and 72.2." (PMID 24516594, 2014). "Akin to HMGA2, PLAG1 is also expressed at higher levels in papillary carcinomas." (PMID 24516594, 2014).
peripheral T cell lymphomas (1 paper, 2019). "Overexpression of Lin28b in transgenic mice results in peripheral T cell lymphomas with a relatively lengthy latency, while Plag1 overexpression alone does not induce disease, so neither alone were predicted to cause AML." (PMID 30890554, 2019).
pituitary tumor (1 paper, 2020). A benign or malignant neoplasm affecting the pituitary gland. "miR-26a expression was significantly higher in pituitary tumor tissues, while PLAG1 mRNA expression was remarkably downregulated in adenomas, especially in IPA tumors." (PMID 33066578, 2020).
rhabdomyosarcoma (1 paper, 2024). A rare aggressive malignant mesenchymal neoplasm arising from skeletal muscle. "Since then, overexpression of PLAG1 has been identified in several cancer types including rhabdomyosarcoma, uterine myosarcoma, lipoblastoma and myoepithelioma." (PMID 38240991, 2024). "In rhabdomyosarcoma, PLAG1 was shown to upregulate insulin-like growth factor 2 (Igf2), a known target gene, alter alpha serine/threonine kinase (AKT) and mitogen-activated protein kinase (MAPK) pathways and positively regulate proliferation and survival of rhabdomyosarcoma cells." (PMID 38240991, 2024).
syringoma chondroid (1 paper, 2025). "Gene fusions such as NDRG1-PLAG1 and TRPS1-PLAG1 have also been reported in rare diseases such as syringoma chondroid.In addition, PLAG1 rearrangement is seen in uterine myxoid leiomyosarcoma (approximately 25% of cases)." (PMID 40276502, 2025).
T-cell acute lymphoblastic leukemia (1 paper, 2018). Acute lymphoblastic leukemia of T-cell origin. "Also, the overexpression of PLAG1 was reported as a driver event of T-cell acute lymphoblastic leukemia." (PMID 29697361, 2018).
triple-negative breast carcinoma (1 paper, 2023). An invasive breast carcinoma which is negative for expression of estrogen receptor (ER), progesterone receptor (PR), and human epidermal growth factor receptor 2 (HER2). "PLAG1 was also reported as a key transcription factor in driving the triple negative breast cancer phenotype." (PMID 36600208, 2023).
type 1 diabetes (1 paper, 2021). "In humans, PLAG1 expression was found to be increased in blood samples of children with pre-type 1 diabetes." (PMID 34063412, 2021).
uveal melanoma (1 paper, 2025). A melanoma derived from melanocytes of the uveal tract. "Additionally, concerning immunosuppressive gens, PLAG1 was significantly positively correlated with TIGIT, CD96, and CD244 in LGG, uveal melanoma, and liver hepatocellular carcinoma, indicating that it may facilitate the formation of a tumor immune-suppressive microenvironment." (PMID 40276502, 2025).